STAT6 (signal transducer and activator of transcription 6)
Diseases named in the same sentence as STAT6 in open-access papers (continued):
Sharing a sentence is not in itself a finding about the gene and the disease.
renal fibrosis (continued). "In addition, recent studies have shown a role for adiponectin/AMPK and JAK3/STAT6 signaling pathways in the development of experimental renal fibrosis and in collagen production by cultured mouse monocytes, providing new potential therapeutic targets in addition to TGF-β/Smad3 signaling." (PMID 27906172, 2016). "STAT6 transcriptionally represses PPAR α and FAO via a cis-inducible element located in the promoter region of the gene, thereby promoting MMT and renal fibrosis." (PMID 39445007, 2024). "The remaining signalling pathways mediating renal fibrosis are STING/TBK1, IL-4Ra/STAT6, Jmjd3/IRF4, STAT6/PPARα, SETD7, NKT/IL-4, BRP-39, STAT-1/TREM-1, MMP-9/Akt, adiponectin/APK, and JAK3/STAT6." (PMID 39445007, 2024). "Another mechanism includes the involvement of STAT6, a Jumonji domain-containing protein-3 (JMJD3)-mediated increased M2 polarization as a critical regulator of myeloid fibroblast activation and renal fibrosis development." (PMID 38201260, 2023). "However, the role and the detailed mechanisms of tubular STAT6 in renal fibrosis remain unclear." (PMID 35046382, 2022). "Collectively, this study uncovered a previously unrecognized function of canagliflozin in FTO in the autophagy modulation through the regulation of SQSTM1 mRNA stability in the renal tubular STAT6/PPARα/FAO axis and renal fibrosis." (PMID 36685533, 2022). "In the present study, we examine the role of signal transducer and activator of transcription 6 (STAT6) in myeloid fibroblast activation, macrophage polarization, and renal fibrosis development in a mouse model of folic acid nephropathy." (PMID 34831280, 2021). "In this study, we examined the effect of a selective STAT6 inhibitor, AS1517499, on myeloid fibroblast activation, macrophage polarization, and development of renal fibrosis in two experimental murine models." (PMID 34512669, 2021). "Recent studies have uncovered that tubular STAT6, a downstream gene of CXCR4, could promote lipid accumulation and renal fibrosis by suppressing FAO in the UUO model through a sis‐inducible element situated in the promoter region of the protein." (PMID 38213100, 2024). "In addition to the STAT6 and PTEN genes, Jumonji structural domain-containing protein-3 (JMJD3) affects renal fibrosis." (PMID 39877385, 2024). "At least, MST1/2 inhibition could reduce the IL-4+IL-13-induced activation of STAT6 and MEK/ERK in macrophage independent and dependent of YAP, and MST1/2 inhibition impaired M2 polarization and renal fibrosis." (PMID 38250155, 2024). "STAT6 inhibition promotes a shift to FAO for energy utilization by inducing PPARα activation in tubular cells, thereby attenuating the lipid accumulation and alleviating renal fibrosis." (PMID 36685533, 2022). "Here, we found that canagliflozin significantly upregulates SQSTM1/P62, promoting PPARα-mediated FAO by inducing autophagy-dependent STAT6 degradation both in TGF-β1-treated HK2 cells and in unilateral ureteral occlusion (UUO) and ischemia–reperfusion (I/R) renal fibrosis mouse models." (PMID 36685533, 2022). "In the present study, we examined the effect of a STAT6-specific inhibitor, AS1517499, on monocyte-to-fibroblast transition, M2 macrophage polarization, and development of renal fibrosis in two murine models of chronic kidney disease induced by ureteral obstruction or folic acid." (PMID 34512669, 2021). "So, it could be inferred that H2S alleviates renal fibrosis in response to UUO by suppressing macrophage infiltration through inhibition of NLRP3 inflammasome via NF-κB and IL-4/STAT6 signaling pathways, which needed to be further proven 57-59." (PMID 33110394, 2020).
Hodgkins lymphoma (23 papers, 2011 to 2025). A heterogeneous group of malignant lymphoid neoplasms of B-cell origin characterized histologically by the presence of Hodgkin and Reed-Sternberg (HRS) cells in the vast majority of cases. "Recurrent mutations in the DNA-binding domain of STAT6 have previously been reported as one of the most frequent in classical Hodgkin lymphoma." (PMID 41201657, 2025). "While somatic STAT6 polymorphisms are mainly associated with various tumor entities such as Hodgkin lymphoma, only recently patients with germline STAT6 GOF disorders have been reported." (PMID 37140667, 2023). "STAT6 mutations in the DNA binding region have been described in Hodgkin lymphoma." (PMID 35145272, 2022). "STAT6 is also often found constitutively phosphorylated in Hodgkin and Reed-Sternberg cells of Hodgkin lymphoma." (PMID 37377751, 2023). "Signal transducer and activator of transcription 6 (STAT6), which is activated by IL-13, was found to be phosphorylated in cell lines of Hodgkin lymphoma." (PMID 35685639, 2022). "In fact, while constitutive phosphorylation of STAT6 is known to be a distinctive feature of classical Hodgkin’s lymphoma, constitutive STAT3 activation is commonly encountered in both Hodgkin’s and non-Hodgkin’s lymphoma patients." (PMID 23593269, 2013). "The third mechanism has been described in Hodgkin lymphomas (classical Hodgkin lymphomas and nodular lymphocyte-predominant Hodgkin lymphomas) and PMBL, in which both high JAK2 expression and p-STAT6 were observed and attributed to SOCS1 mutations via the disruption of a negative feedback loop." (PMID 37835560, 2023). "It should be noted that IL4R mutations have been observed in Hodgkin lymphoma previously, but were not discussed in the context of STAT6 activation." (PMID 37910143, 2023). "document the functional role of mutant STAT6 in maintaining tumor cell viability and show that genetic and functional mutations synergize with disruption of JAK-STAT pathway inhibitors to promote the growth of classical Hodgkin lymphoma." (PMID 36531013, 2022). "To date, aberrant regulation of the JAK1/2-STAT6 pathway has been identified in different pathological conditions and activated STAT6 has been found in patient samples isolated from Hodgkin lymphomas, cutaneous T cell lymphomas, adult T cell leukemia and B-lymphomas." (PMID 34359628, 2021). "Besides, constitutive activation of STAT6 is found in a variety of malignancies, including mediastinal primary large B-cell lymphoma, Hodgkin's lymphoma, prostate cancer and cutaneous T-cell lymphoma." (PMID 27533463, 2016). "Interestingly, STAT6 and STAT1 seem to play opposite roles in Hodgkin lymphoma; upon STAT6 knockdown, STAT1 was found to be upregulated in response." (PMID 26073592, 2015). "Moreover, STAT6 has also been found to be activated spontaneously in human cancers such as prostate cancer, B cell lymphoma and Hodgkin's lymphoma suggesting that an active STAT6 signaling may be beneficial for cancer cell growth." (PMID 22162773, 2011). "This analysis highlighted that many KEGG Hodgkin lymphoma pathway genes are jointly induced by TES1 and TES2 signaling in LCLs, including CCL22, BCL3, cRel, IRF4, STAT3, STAT6, and CD70, each of which has prominent roles in Hodgkin lymphoma pathogenesis." (PMID 38009935, 2023). "The Hodgkin lymphoma cell line HDLM-2 has been demonstrated to show constitutive phosphorylation of JAK1 and JAK2, and STAT1, STAT3, STAT5 and STAT6." (PMID 26131691, 2015). "It acts as a causative factor for autocrine and paracrine activation of canonical and noncanonical NF-κB signaling as well as promotes JAK2/STAT6 signaling in Hodgkin lymphoma resulting in prevention of apoptosis." (PMID 40186177, 2025).
helminth infection (21 papers, 2011 to 2025). "Loci shown to be associated with susceptibility to helminth infection include 5q31-q33, signal transducer and transcriptional activator 6 (STAT6) and ligase 4 (LIG4)." (PMID 33692795, 2021). "The production of Th2 cytokines during helminth infection is associated with the expression of the transcription factor signal transducer and activator of transcription 6 (STAT6) by alternatively activated macrophages." (PMID 30467504, 2018). "To next evaluate the impact of IL-6 deficiency on the innate immune response to H. polygyrus infection, we then assessed the generation of eosinophilia, which in other helminth infections can occur independently of the adaptive Th2 compartment in nu/nu, STAT-6−/−, and RAG-deficient animals." (PMID 24185641, 2014). "In mice deficient in STAT6, viral loads were reduced when compared to wild-type controls indicating that the induction of STAT6-dependent alternatively activated macrophages during helminth infection can impede the induction of antiviral innate and adaptive immunity." (PMID 30467504, 2018). "LOF mutations in STAT6 result in defective Th2 responses, affecting the body’s ability to defend against helminth infections, while GOF mutations in STAT6 lead to an inherited allergic syndrome." (PMID 40140631, 2025). "STAT6 is one of the canonical transcription factors necessary for establishing and maintaining type 2 immune dominance during helminth infection." (PMID 38079450, 2023). "This indicates that AAM polarization can be induced in macrophages of Mac-STAT6 mice in another helminth infection model." (PMID 37018382, 2023). "Further, hypercontractility of smooth muscle cells evoked by IL-4 and IL-13 was shown to be dependent on STAT6 in helminth infection." (PMID 37018382, 2023). "Our foregoing observations in STAT6−/− BMT recipients also suggested that regulatory IL-4 production by recipients after helminth infection can act on recipient IL-4–responsive cell populations to regulate GVHD." (PMID 37294277, 2023). "To verify that STAT6 acts downstream of OGT to control helminth infection-induced epithelial hyperplasia, we generated Ogti∆IEC-TgS6vt mice with concurrent STAT6vt overexpression and Ogt deletion in IECs." (PMID 36232438, 2022). "In contrast, the specific expression of STAT6 in IECs promotes secretory cell differentiation (including tuft and goblet cells) and protects against helminth infection." (PMID 36232438, 2022). "It is known that IL-4/IL-13-mediated STAT6 signaling plays a central role in promoting tuft and goblet cell hyperplasia in the small intestine during helminth infection." (PMID 36232438, 2022). "It has been reported that chronic helminth infection induces a host Th2-type response bias and that STAT6 signaling is central for this phenotype." (PMID 35617354, 2022). "Collectively, these data show that epithelial SIRT6 is sufficient to drive helminth infection-induced epithelial remodeling through modulating STAT6 activity." (PMID 36057627, 2022). "Stat6−/− mice exhibit blunted tuft and goblet cell hyperplasia and type 2 immune responses upon helminth infection." (PMID 36232438, 2022). "As well as impeding the efficacy of anti-viral immunity, the expression of IL-4 and activation of the transcription factor STAT6 during helminth infection in mice can also promote the reactivation of a latent γ-herpesvirus infection." (PMID 30467504, 2018). "This important finding echoes with recent data demonstrating that ongoing helminth infection impairs virus-specific T-cell immunity via a STAT-6-dependent alternative activation of macrophages differentiation." (PMID 28759590, 2017). "Finally, the role of T cells during helminth infections has been widely reported, mainly due to its IL-4 production in a STAT6-dependent fashion, inducing the anti-inflammatory profile needed to generate protection." (PMID 38392907, 2024).
helminth infection (continued). "In addition, SIRT6 can promote intestinal tuft cell development through activation of STAT6, which subsequently enhances intestinal type 2 immune responses to protect mice from helminth infection." (PMID 39253083, 2024). "Our data clearly support our hypothesis that STAT6 mediates OGT’s function in regulating mucosal type 2 immune responses against helminth infection." (PMID 36232438, 2022). "Selective expression of constitutively activated STAT6 in IECs promotes proliferation and differentiation of tuft and goblet cells and protects against gastrointestinal helminth infections, indicating activation of STAT6 in epithelial cells is critical for secretory cell differentiation." (PMID 36057627, 2022). "Therefore, STAT6 activity must be fine-tuned for proper type 2 immune responses to helminth infections." (PMID 36057627, 2022). "In helminth infections, alternatively activated macrophages (M2), whose activation occurs mainly via the IL-4/STAT6 pathway, have a major role in mediating protection against excessive inflammation, and has been associated with both tissue repair and parasite clearance." (PMID 31810203, 2019). "However, similar to the ability of IL-4 and IL-13 to induce the alternatively activated phenotype in macrophages in the context of helminth infections, fungus-induced Arg1 was also found to be at least partially dependent on IL-4Rα/STAT6." (PMID 21246055, 2011). "Indeed, we find increased host mortality with STAT6 KO-adapted worm infection." (PMID 38079450, 2023). "In addition to that, polymorphisms at some loci of IL13, STAT6 and IL10 genes have been associated not only with total IgE levels, but also with other helminthic infections such as Ascaris infections." (PMID 36889485, 2023). "However, helminthic infections or their derivatives may exert their effect on antimetabolic diseases through other different mechanisms, such as activating the STAT6 signaling pathway, changing the intestinal microbiota." (PMID 34901005, 2021). "STAT6 was proposed to provide a nonredundant signal to Treg expansion, which we showed to depend on STAT6- (Th2)-dependent TGFβ activation after helminth infection." (PMID 39796136, 2024). "In contrast, in uninfected mice whose ability to upregulate Th2 signaling is impaired (IL-4−/−, STAT6−/−, or IL-4Rα−/− genotype), these numbers remained low and did not rise above baseline levels after helminth infection." (PMID 37294277, 2023). "Stat6−/− mice failed to generate helminth infection-induced tuft and goblet cell hyperplasia, demonstrating a requirement for STAT6 activity in the protective type 2 immune responses." (PMID 36057627, 2022). "Thus, helminth infection promotes survival of recipient T cells in the spleen and MLNs in WT but not IL-4−/−, STAT6−/−, or IL-4Rα−/− BMT recipient mice when they receive WT C57BL/6 donor cells." (PMID 37294277, 2023). "In the process of M2 polarization and helminth infection, the immune response of the host to helminth infections is strikingly dominated by a Th2 response with a significant production of IL-4, IL-10, IL-13, and the STAT3/STAT6 signaling pathways have been detected." (PMID 28983296, 2017). "We next tested a large cohort of BMT mice for CD3 and H2b expression, discovering that in WT mice a significant portion of CD3+ cells did not stain for H2b− following helminth infection but that almost all CD3+ cells from IL-4−/−, STAT6−/−, or IL-4Rα−/− BMT recipients did." (PMID 37294277, 2023).
lung carcinoma (21 papers, 2011 to 2025). "STAT6 deficiency with siRNA inhibits carcinogen-induced lung cancer growth and improves prognosis in cancer transplantation mice model." (PMID 35600336, 2022). "In a urethane-induced primary lung cancer model, STAT6 deficiency inhibits tumor growth and improves prognosis." (PMID 31798581, 2019). "PRKCSH expression level was negatively associated with STAT6 levels in lung cancer tissues." (PMID 38571496, 2024). "Nevertheless, the role of STAT6 signaling in lung carcinogenesis and lung cancer proliferation and its underlying mechanisms remain unclear." (PMID 31798581, 2019). "Experimental evidence supports the role of STAT3 and STAT6 in reducing tumor growth and metastasis in breast and lung cancer models." (PMID 39827422, 2025). "Lung cancer growth and metastasis were also effectively controlled through STAT6-dependent M2 polarization inhibition by anti-CHI3L1 antibodies." (PMID 36615523, 2022). "This study provides the importance of anti‐Chi3L1 antibody regulating tumor growth and metastasis through STAT6‐dependent M2 polarization inhibition in lung cancer." (PMID 34861103, 2022). "One report demonstrates that 15-PGDH is activated by IL-4 in association with JAK/STAT6, MAPK, PI3K, and PKC signaling in lung cancer cells." (PMID 34194517, 2021). "Positive p-STAT6 staining was detected in the primary tumors of 5 out of 7 EML4-ALK-positive lung cancer patients, while p-JAK2 appeared in all seven primary tumors." (PMID 34090412, 2021). "A study in 2007 showed that the actions of STAT6 in lung cancer were directly involved in COX-2 expression." (PMID 31075146, 2019). "Immunological microarray analyses revealed that in lung carcinoma tissue, CD11b+ cells are increased and the IHC scores of CD11b and STAT6 are higher than in lung para-carcinoma tissue." (PMID 31798581, 2019). "STAT6 mRNA expression is also higher in PBMCs than in the human lung cancer cell lines A549, H1299, SPC-A1, and SK-MES-1." (PMID 31798581, 2019). "Our previous studies showed that STAT6 expression is higher in lung carcinoma than para-carcinoma tissues (unpublished data)." (PMID 31798581, 2019). "We demonstrated in this study that urethane is a good choice for establishing a lung cancer model in WT and STAT6−/− mice." (PMID 31798581, 2019). "Here we present data demonstrating that STAT6 is highly expressed in lung carcinoma tissue and predominantly in the interstitial CD11b+ cells." (PMID 31798581, 2019). "STAT6 protein expression is significantly increased in lung carcinoma tissue compared to para-carcinoma tissue." (PMID 31798581, 2019). "In conclusion, our findings indicate that IL-4/STAT6 signaling in CD11b+ cells promotes lung cancer progression by triggering an IL-4 positive feedback loop and increasing M2 myeloid cells." (PMID 31798581, 2019). "In the present study, we established a urethane-induced primary lung cancer model in STAT6 knockout mice to explore the effects of STAT6 on lung cancer and to further investigate the interaction between STAT6 and the pulmonary TME." (PMID 31798581, 2019). "Laser confocal imaging of human lung cancer sections showed that STAT6 is mainly expressed in the interstitial CD11b+ immune cells." (PMID 31798581, 2019). "In the present study we have, for the first time, shown the inverse relationship of STAT6 with the cholesterol biosynthesis in lung cancer cells." (PMID 22162773, 2011). "In view of this, we sought to study the effect of STAT6 silencing on genome wide gene expression patterns in NCI-H460 cells (lung cancer epithelial)." (PMID 22162773, 2011). "Herein, we show for the first time that direct inhibition of STAT6 can lead to an increase in cholesterol levels in lung cancer cells." (PMID 22162773, 2011). "STAT6 knockout mice have a higher tolerance to lung cancer metastasis than wild-type mice." (PMID 35600336, 2022). "P-JAK2 and p-STAT6 appeared in the cytoplasm of lung cancer cells positive for EML4-ALK." (PMID 34090412, 2021).